CMTM5 (CKLF like MARVEL transmembrane domain containing 5)
Synonyms: CKLFSF5; FLJ37521
Tractability: Antibody: UniProt predicts a signal peptide or a membrane-spanning region.
Gene: Protein-coding gene on chromosome 14 (23,376,627 to 23,379,772, forward strand). Ensembl gene ENSG00000166091.
Subcellular location: Membrane
Subcellular location (Human Protein Atlas): Golgi apparatus; Vesicles
Gene Ontology:
Molecular function: protein binding
Cellular component: membrane
Genetic constraint (gnomAD): Loss-of-function variants: 25 observed, 28.04 expected, observed/expected ratio (o/e) 0.89, 90% interval 0.65 to 1.25. The upper end of that interval is the gene's LOEUF score, 1.25, which puts it in group 5 of 6, group 1 being the genes least tolerant of losing a copy. Missense variants: 292 observed, 303.75 expected, observed/expected ratio (o/e) 0.96, 90% interval 0.87 to 1.06. Synonymous variants: 98 observed, 120.7 expected, observed/expected ratio (o/e) 0.81, 90% interval 0.69 to 0.96.
Homologues: Orthologues: chimpanzee CMTM5 (97% identical), rat Cmtm5 (63% identical), guinea pig CMTM5 (62% identical), pig CMTM5 (62% identical), rabbit CMTM5 (62% identical), dog CMTM5 (61% identical), mouse Cmtm5 (59% identical), macaque CMTM5 (54% identical), tropical clawed frog cmtm5 (29% identical), Caenorhabditis elegans F28H1.4 (12% identical), Caenorhabditis elegans F47B3.3 (11% identical). Paralogues in human: CMTM3 (27% identical), PLP2 (19% identical), CMTM6 (15% identical), CMTM2 (13% identical), CKLF (13% identical), CMTM4 (13% identical), CMTM1 (13% identical), PLLP (13% identical), MALL (12% identical), MAL (11% identical), CMTM8 (10% identical), MARVELD1 (10% identical), and 2 more.
Diseases named in the same sentence as CMTM5 in open-access papers:
CMTM5 is named in the same sentence as 26 diseases in open-access papers, as found by Europe PMC text mining. Sharing a sentence is not in itself a finding about the gene and the disease. The quoted sentences say what the papers report.
prostate carcinoma (7 papers, 2017 to 2025). A carcinoma that arises from epithelial cells of the prostate gland. "For example, CMTM5 overexpression significantly inhibited prostate cancer cell proliferation, migration and invasion, and promoted cell apoptosis compared with vector control cells in vitro." (PMID 39166861, 2024). "CMTM5 acts as a tumor-suppressor gene, and it is downregulated in several cancers, such as myeloid leukemia, ovarian cancer, prostate cancer, cervical carcinoma, and pancreatic cancer." (PMID 36552262, 2022). "In addition, in HCC and prostate cancers, the expression of CMTM5 is negatively associated with activation of the PI3K/AKT pathway 48,55, which is downstream of EGFR signaling, thus suggesting that CMTM5 may inhibit tumor growth and metastasis by targeting AKT48,55." (PMID 32944388, 2020). "Recently, it has been reported that ectopic expression of CMTM5 in prostate cancer cell decreased Akt activity." (PMID 29213215, 2017). "CMTM3 and CMTM5, which have 42% homology and contain a typical CpG island, generally tend to be regarded as tumor suppressors because of their low expression in gastric cancer, prostate cancer, and HCC." (PMID 40179060, 2025). "Besides, CMTM5 was shown to be abnormally inhibited in prostate cancer and its overexpression was found to suppress the growth of prostate cancer cells." (PMID 39166861, 2024). "CMTM5-v1 is found to inhibit prostate cancer (PCa) cells through the EGFR signaling pathway, and the loss of CMTM5 may be involved in the occurrence and development of PCa caused by deregulated EGFR." (PMID 33585698, 2021). "Moreover, ectopic expression of CMTM5 in prostate cancer cell line DU145 led to significant inhibition of cell proliferation and migration." (PMID 29213215, 2017). "Moreover, a recent study has reported that CMTM5-v1, an alternative splicing protein isoform of CMTM5, may promote the response sensitivity of prostate cancer cells to Gefitinib, a tyrosine kinase inhibitor targeting the EGFR56." (PMID 32944388, 2020). "CMTM5’s expression is negatively correlated with PI3K/AKT pathway activation in liver cancer and prostate cancer." (PMID 39948411, 2025). "It has been reported that CMTM5 acted as a tumour-suppressor gene and was specifically down-regulated in many human cancers, such as cervical carcinoma, pancreatic cancer, myeloid leukemia, ovarian cancer, oral squamous cell carcinoma (OSCC) and prostate cancer." (PMID 29213215, 2017).
hepatocellular carcinoma (6 papers, 2017 to 2024). A malignant tumor that arises from hepatocytes. "A previous study reported that low expression of CMTM5 in hepatocellular carcinoma significantly correlated with poor overall survival." (PMID 38223763, 2024). "Reference 1 Guan L, Ji D, Liang N, Li S and Sun B (2018) Up-regulation of miR-10b-3p promotes the progression of hepatocellular carcinoma cells via targeting CMTM5." (PMID 37219053, 2023). "The current study aimed to investigate the expression and function of CMTM5 in human hepatocellular carcinoma (HCC)." (PMID 29213215, 2017). "Several members, such as CMTM3, CMTM4, CMTM5 and CMTM7, have been documented to exhibit tumor suppressor functions in hepatocellular carcinoma cells." (PMID 33101541, 2020).
cervical carcinoma (4 papers, 2017 to 2023). A carcinoma arising from either the exocervical squamous epithelium or the endocervical glandular epithelium. "Compared with normal samples, the expression of CMTM5 in cervical cancer samples was significantly downregulated, suggesting that CMTM5 plays an important role in the occurrence and development of cervical cancer." (PMID 37654657, 2023). "A previous study suggested that CMTM5 is a tumor suppressor that is frequently methylated and thus loses function in cancer, including cervical cancer." (PMID 35574500, 2022). "Overexpression of CMTM5 in cervical carcinoma cell lines Hela and SiHa could induce cell apoptosis mainly through caspase-dependent pathway." (PMID 29213215, 2017).
liver cancer (3 papers, 2018 to 2025). An epithelial or non-epithelial malignant neoplasm that arises from the liver. "miR-10b-3p expression facilitates the pathogenesis of liver cancer by interacting with CMTM5." (PMID 33428596, 2021).
breast carcinoma (2 papers, 2019 to 2024). "In this study, we also found that lower expression of CMTM5 was associated with inferior response to chemotherapeutics of breast cancers." (PMID 31998718, 2019). "Although our study highlights the prognostic value of CMTM5 in breast cancer and predicts several potential pathways implicated in its function, more studies are warranted so as to elucidate the specific roles of CMTM5 and underlying mechanisms that affect breast cancer development and progression." (PMID 31998718, 2019). "In breast cancer patients, the expression level of CMTM5 and CMTM7 is decreased, while the expression level of CMTM6 is increased." (PMID 38223763, 2024). "The analyses involving MEXPRESS also indicated that the CMTM5 mRNA expression level was significantly lower in breast cancer tissues than in normal tissues and correlated with ER (P = 5.76e−5), PR (P = 3.84e−6), and menopause status (r = −0.0954)." (PMID 31998718, 2019). "We found that the mRNA expression levels of CMTM5 in breast cancer tissues were still significantly lower than in normal tissues after stratification by tumor stage, nodal stage, histologic subtypes, and breast cancer subtypes." (PMID 31998718, 2019). "The mRNA expression level of CMTM5, in particular, was significantly downregulated in breast cancer; moreover, high mRNA expression level of CMTM5 was significantly associated with better relapse-free survival." (PMID 31998718, 2019). "We used UALCAN to assess CMTM5 mRNA expression levels in breast cancer according to clinicopathological characteristics." (PMID 31998718, 2019). "As per the analyses involving UALCAN, a significantly higher promoter methylation level of CMTM5 was observed in breast cancer tissues than in normal tissues (1.17-fold, P < 1e−12), which was also confirmed upon using MethHC (P < 0.01)." (PMID 31998718, 2019). "However, low mRNA levels of CMTM5 were associated with lower RFS in our study, while ER and PR positive diseases were associated with better survival outcomes of breast cancer." (PMID 31998718, 2019). "With regard to the immunohistochemical staining of CMTM5, among the 11 breast cancer patients with pertinent data in the Human Protein Atlas, only one (9.1%) showed low expression of CMTM5, whereas no expression of CMTM5 in tumor tissues was observed in the other 10 (90.9%) patients." (PMID 31998718, 2019). "According to our study, CMTM5 may be available as potential target for development of new treatment strategies of breast cancer." (PMID 31998718, 2019). "By browsing biomolecular regulatory networks for genes of interest and via functional enrichment analyses, we found that CMTM5 is closely correlated with 28 genes that are involved in pathways that potentially play a crucial role in breast cancer development and progression." (PMID 31998718, 2019). "In addition to determining the mRNA expression levels of several CMTM family members, we herein used UALCAN and found that CMTM5 was significantly dysregulated in breast cancer relative to other CMTM family members (45.36-fold vs. 1.02–3.72-fold)." (PMID 31998718, 2019). "We believe that our findings should be helpful for investigating the detailed function and potential carcinogenic mechanisms of CMTM5 in breast cancer, which might promote the development of a novel target treatment for breast cancer." (PMID 31998718, 2019). "In breast cancer tissues, the mRNA expression levels of only CMTM1, CMTM5, CMTM6, and CMTM7 were measured." (PMID 31998718, 2019). "The mRNA expression levels of CMTM5 and CMTM7 were significantly downregulated while those of CMTM1 and CMTM6 were significantly upregulated in breast cancer tissues than in corresponding normal tissues." (PMID 31998718, 2019). "The expression level of CMTM1, 2, 4 and 8 in breast cancer are decreased, while the expression level of CMTM5 is not different between healthy individuals and patients with metastatic breast cancer." (PMID 38223763, 2024).
breast carcinoma (continued). "In conclusion, using comprehensive bioinformatic analysis, we report that CMTM5 is a putative tumor suppressor gene that can serve as a potential negative prognostic biomarker in breast cancer." (PMID 31998718, 2019).
glioma (2 papers, 2022 to 2024). A benign or malignant brain and spinal cord tumor that arises from glial cells (astrocytes, oligodendrocytes, ependymal cells). "The UALCAN database predicted downregulation of CMTM5 expression in glioma, and low expression of CMTM5 was associated with poor survival outcomes." (PMID 39166861, 2024). "Collectively, these findings indicate that CMTM5 overexpression promoted erastin‐induced ferroptosis and inhibited cell growth of glioma cells." (PMID 39166861, 2024). "Collectively, these findings suggest that CMTM5 knockdown augmented cell growth and suppressed ferroptosis of glioma cells by regulating WWP2." (PMID 39166861, 2024). "CMTM5 knockdown led to increased cell viability, proliferation, migration, and invasion of glioma cells, while WWP2 silencing compromised these alterations caused by CMTM5 knockdown." (PMID 39166861, 2024). "Future studies should aim to overcome the limitations of this study to explore the role of CMTM5/WWP2/LATS2 signaling in glioma." (PMID 39166861, 2024). "Knockdown of WWP2 abolished CMTM5 silencing‐promoted cell growth and invasion and CMTM5 silencing‐suppressed ferroptosis of glioma cells." (PMID 39166861, 2024). "Our study confirmed that CMTM4 and CMTM5 are highly expressed in glioma with lower grade and better prognostic subtypes; however, the specific molecular mechanism warrants further investigation." (PMID 35252165, 2022). "CMTM5 overexpression inhibited cell growth and invasion and promoted ferroptosis of glioma cells." (PMID 39166861, 2024). "Besides, LATS2 downregulation promoted cell viability, proliferation, migration, and invasion of glioma cells, whereas WWP2 knockdown or CMTM5 overexpression reversed these changes caused by LATS2 downregulation." (PMID 39166861, 2024). "In the present study, online database predicted reduced expression of CMTM5 in glioma." (PMID 39166861, 2024). "Collectively, this is the first study to demonstrate that CMTM5 overexpression may suppress cell growth and invasion and promote ferroptosis of glioma cells by reducing WWP2 expression." (PMID 39166861, 2024). "However, LATS2 knockdown‐mediated reduction of Fe2+, lipid ROS, and MDA levels in erastin‐induced glioma cells was reversed by WWP2 knockdown or CMTM5 overexpression." (PMID 39166861, 2024). "However, the potential role of CMTM5 in glioma and the underlying molecular mechanism is not well characterized." (PMID 39166861, 2024). "Furthermore, CMTM5 overexpression inhibited the growth and invasion and promoted ferroptosis of glioma cells, all of which indicated that CMTM5 could delay glioma progression." (PMID 39166861, 2024). "CMTM5 regulated Hippo/YAP signaling to inhibit cell growth and invasion and to promote ferroptosis in glioma by regulating WWP2‐mediated LATS2 ubiquitination, thereby attenuating glioma progression." (PMID 39166861, 2024). "Here, we found that WWP2 knockdown‐mediated reduction of WWP2 and YAP1 expression and elevation of LATS2 and p‐YAP1 levels in glioma cells was reversed by the combination of sh‐WWP2 and sh‐CMTM5 transfection." (PMID 39166861, 2024). "In conclusion, we propose that CMTM5 may regulate Hippo/YAP axis to suppress cell growth and invasion and accelerate cell ferroptosis in glioma by inhibiting WWP2‐mediated LATS2 ubiquitination." (PMID 39166861, 2024). "However, it is still unclear whether the CMTM5/WWP2/LATS2 axis is involved in angiogenesis in glioma and the treatment of glioma with bevacizumab." (PMID 39166861, 2024). "we did not investigate whether CMTM5/WWP2/LATS2 signaling affects DNA repair enzyme O6Meg DNA methyltransferase (MGMT) status in glioma." (PMID 39166861, 2024). "This is the first study to demonstrate that CMTM5, which suppressed WWP2 expression through interacting with WWP2 protein, inhibited cell growth and promoted ferroptosis by attenuating WWP2‐mediated LATS2 ubiquitination and degradation, thereby alleviating glioma progression." (PMID 39166861, 2024).
glioma (continued). "Moreover, Co‐IP analysis validated the interaction between CMTM5 and WWP2 in glioma cells." (PMID 39166861, 2024).
Hypertension (2 papers, 2025 to 2026). The presence of chronic increased pressure in the systemic arterial system. "Six genes (PTGS2, TBXA2R, ZNF101, KCNJ2, MSRA, and CMTM5) have been reported to be associated with hypertension." (PMID 39854379, 2025). "Among those, CMTM5, ITGA2B, and SLC24A3 are implicated in platelet function and cardiovascular complications, whereas ENOSF1 has been previously linked to hypertension." (PMID 41500120, 2026).
Sepsis (2 papers, 2020 to 2023). Sepsis is defined as life-threatening organ dysfunction caused by a dysregulated host response to infection. "All of these are associated with MYL9 in pediatric sepsis and in pediatric septic shock, except for CMTM5 in the latter." (PMID 32318053, 2020). "Expression of sepsis-specific biomarkers PLXNB3, ITGB3, CETP, CMTM5 and PF4 correlated positively with each other at the Day1 time point and to a slightly lesser degree with MIA and CRP." (PMID 38332914, 2023). "Gene entities shared between sepsis and severe sepsis response hubs are; TDRD9 – LIN7A, GPR84 – ENTPD7, PYCT1A and ZDHHC19, CD177 – DDAH2 and RGL4, SLC16A3 – DENND3 and MBD6, MYL9 – CMTM5, ITGB3, ITGA2B, NRGN, SELP and TREML1." (PMID 32318053, 2020). "It interacts with TREML1, CMTM5, TGFB1l1, and ITGA2B in adult SIRS, among others and TGFB1l1 only in adult sepsis." (PMID 32318053, 2020). "CMTM5, SELP, and TREML1 were also observed in pediatric resolved SIRS, in addition to ALOX12 (arachidonate 12-lipoxygenase, 12S type), which was also seen in pediatric sepsis." (PMID 32318053, 2020).
autoimmune disease (1 paper, 2023). A disorder resulting from loss of function or tissue destruction of an organ or multiple organs, arising from humoral or cellular immune responses of the individual to their own tissue constituents. "This study comprehensively addresses the involvement of the protein CKLF-like Marvel transmembrane domain-containing family member 5 (CMTM5) in the context of demyelination and cytodegenerative autoimmune diseases, particularly multiple Sclerosis (MS)." (PMID 37626895, 2023).
benign prostatic hyperplasia (1 paper, 2020). A non-cancerous nodular enlargement of the prostate gland. "In this study, we found that CMTM5 was expressed in benign prostatic hyperplasia (BPH) tissues but was undetectable in PCa cells." (PMID 32328181, 2020).
cholangiocarcinoma (1 paper, 2022). A carcinoma that arises from the intrahepatic biliary tree (intrahepatic cholangiocarcinoma) or from the junction, or adjacent to the junction, of the right and left hepatic ducts (hilar cholangiocarcinoma). "For example, miR-10b-3p upregulation was shown to enhance HCC progression via suppressing CMTM5 expression, while miR-885-5p was able to target GALNT3 and to thereby inhibit PI3K/AKT/MMP signaling to disrupt intrahepatic cholangiocarcinoma metastasis." (PMID 36217480, 2022).
COVID-19 (1 paper, 2022). A disease caused by infection with severe acute respiratory syndrome coronavirus 2. "Two of the shared-six genes between the McClain and Lee data were related to platelet function: glycoprotein IX platelet (GP9) and CKLF-like MARVEL transmembrane domain-containing protein 5 (CMTM5), both of which were consistently upregulated in a COVID-19 specific manner across the datasets." (PMID 35991542, 2022).
demyelination (1 paper, 2023). "Since CMTM5 expression was found to be reduced in demyelination models, we asked whether knocking down Cmtm5 per se has an effect on the responsiveness of oligodendroglia to ER stress." (PMID 37626895, 2023).
glioblastoma multiforme (1 paper, 2024). "First, predictive analysis using the UALCAN database showed lower expression of CMTM5 in glioblastoma multiforme." (PMID 39166861, 2024).
post-traumatic stress disorder (1 paper, 2020). An anxiety disorder precipitated by an experience of intense fear or horror while exposed to a traumatic (especially life-threatening) event. "Another module downregulated in the early adversity group was related to platelet activation and wound healing (hub genes: GP9, CMTM5, TUBB1, GNG11, PF4), and resembled a co-expression module previously found over-expressed in post-traumatic stress disorder resilient soldiers." (PMID 32066736, 2020).
renal cell carcinoma (1 paper, 2020). "CMTM5 expression is low in renal cell carcinoma (RCC), metastatic renal cell adenocarcinoma, metastatic clear renal cell adenocarcinoma, and the human kidney cancer line HK257." (PMID 32944388, 2020).
serous ovarian cancer (1 paper, 2019). "CMTM5 is located in 14q11.2, a chromosome region which have showed gains significantly more frequently in the chemoresistant disease subgroup compared to the chemosensitive disease subgroup in serous ovarian cancer." (PMID 31998718, 2019).